DNAAF9 (dynein axonemal assembly factor 9)
Description:
Dynein axonemal assembly factor that regulates the transport and activation of ciliary outer dynein arms (ODAs), which are the main force generators in cilia. Essential for cilia movement and motility. Inhibits dyneins by reducing the affinity of ODAs for microtubules and hence inactivating the dyneins in the cytoplasm; the inhibition is relieved once dyneins enter the cilia (By similarity). May act as an effector for ARL3.
Synonyms: C20orf194; DKFZp434N061
Tractability: No criterion of Open Targets' tractability assessment is met for any kind of drug.
Safety:
Unwanted effects reported when the protein is acted on. In parentheses: how it was acted on, where the effect was seen, and who reports it.
anemia (source: ClinPGx)
Gene: Protein-coding gene on chromosome 20 (3,249,306 to 3,407,940, reverse strand). Ensembl gene ENSG00000088854.
Subcellular location (Human Protein Atlas): Cytosol; Nucleoli fibrillar center
Gene Ontology:
Molecular function: protein binding
Genetic constraint (gnomAD): Loss-of-function variants: 23 observed, 43.31 expected, observed/expected ratio (o/e) 0.53, 90% interval 0.38 to 0.75. The upper end of that interval is the gene's LOEUF score, 0.75, which puts it in group 3 of 6, group 1 being the genes least tolerant of losing a copy. Missense variants: 479 observed, 548.87 expected, observed/expected ratio (o/e) 0.87, 90% interval 0.81 to 0.94. Synonymous variants: 191 observed, 207.52 expected, observed/expected ratio (o/e) 0.92, 90% interval 0.82 to 1.04.
Homologues: Orthologues: chimpanzee DNAAF9 (99% identical), macaque DNAAF9 (97% identical), dog DNAAF9 (92% identical), rabbit DNAAF9 (90% identical), rat Dnaaf9 (85% identical), pig DNAAF9 (85% identical), mouse Dnaaf9 (85% identical), guinea pig DNAAF9 (85% identical), tropical clawed frog dnaaf9 (65% identical), zebrafish dnaaf9 (51% identical).
Diseases named in the same sentence as DNAAF9 in open-access papers:
DNAAF9 is named in the same sentence as 3 diseases in open-access papers, as found by Europe PMC text mining. Sharing a sentence is not in itself a finding about the gene and the disease. The quoted sentences say what the papers report.
ciliopathies (1 paper, 2025). "Taken together, we propose that DNAAF9 may be functionally important in maintaining ciliary motility in mammals and should be considered as a candidate for syndromic ciliopathies with combined features characteristic of primary and motile cilia defects." (PMID 41023246, 2025). "Although DNAAF9 variants have not been reported in persons with ciliopathies, its broad expression pattern in humans and interaction with ARL3 across different tissues indicate that it could have critical roles in tissues with both primary and motile cilia." (PMID 41023246, 2025).
Hydrocephalus (1 paper, 2025). Hydrocephalus is an active distension of the ventricular system of the brain resulting from inadequate passage of CSF from its point of production within the cerebral ventricles to its point of absorption into the systemic circulation. "Indeed, Dnaaf9−/− mouse mutants develop mild to severe hydrocephalus, consistent with a role in contributing to proper motile cilia functions." (PMID 41023246, 2025).
DNAAF9 also shares sentences with these, for which no sentence is quoted: cancer (1 paper).